CD9 (CD9 molecule)
Diseases named in the same sentence as CD9 in open-access papers (continued):
Sharing a sentence is not in itself a finding about the gene and the disease.
cancer (continued). "In the light of data and results collected, we next investigated if EVs deriving from CD9-RFP transfected HEK293 cells were able to horizontally transfer the exogenous cargo protein to recipient cancer cells." (PMID 36579638, 2023). "Dissociating exosomes from OC serum has been reported using an antibody-functionalized microfluidic framework to identify biomarkers present in cancer exosome membranes (e.g., EpCAM, CD9)." (PMID 37082219, 2023). "A CD9-dependent invasion of cancer cells into MSCs, with phenomena of entosis (cell-in-cell), was also reported by Rappa and colleagues." (PMID 37371036, 2023). "Of note, studies using the antibody clone m31-15 consistently report the good prognostic value of high CD9 in all cancer types." (PMID 37007105, 2023). "A growing body of evidence points to the important role of CD9 in various physiological processes and cancer." (PMID 37007105, 2023). "There is evidence to suggest that CD9 is involved in the packaging and release of exosomes by cancer cells." (PMID 37475778, 2023). "In summary, CD9 appears to play an important role in the communication between cancer cells and their microenvironment via exosomes." (PMID 37475778, 2023). "The following TSPANs have been involved in enhancing cancer therapy resistance: CD9, CD81, TSPAN1, TSPAN3, TSPAN31, CD82 and CD63." (PMID 36941633, 2023). "The tetraspanins CD63, CD81 and CD9 are commonly used as surface markers of EVs, but are ubiquitously expressed and cannot differentiate EVs that are released by cancer cells and by normal cells." (PMID 36973758, 2023). "Regardless of the molecular mechanism, we have shown that the cancer cell transformation can be inhibited by the application of a Fab fragment derived from the anti-CD9 antibody, which prevents the uptake of EVs." (PMID 37371036, 2023). "CD9 is found at the cell surface and the membrane of exosomes affecting cancer progression and therapy resistance." (PMID 37007105, 2023). "Obviously, tetraspanin CD9 plays a complex role both in physiological conditions as well as in many diseases including cancer." (PMID 37007105, 2023). "The growth factor HBEGF, which is highly expressed in Monocytes, Neutrophils, Dendritic Cells, GMP Cells, Macrophages, and various Epithelial Cells, interacts with CD9 expressed in Cancer Cells to help mediate tumorigenesis and proliferation." (PMID 36401283, 2022). "Our results also expand the previous conclusion that CD9 is conservatively expressed in EVs into cancer stem cells, which highlights the utility of CD9 as an EVs marker across variable cell types." (PMID 35269915, 2022). "Apart from a variety of biological activities, such as signal transduction, inflammation regulation, and cell adhesion, CD9 is reportedly involved in the oncogenesis and metastasis of cancer." (PMID 36212136, 2022). "CD9 is a transmembrane protein that is expressed on several cell types including cancer cells and MSCs, and on the exosomes released from cells." (PMID 35103937, 2022). "In cancers, overexpression of CD-9 induces osteoclast bone resorption in the bone micro environment." (PMID 35928720, 2022). "An earlier proteomics study suggested that the expression of exosomal CD9 significantly varied among cancer tissues and relevant normal tissues." (PMID 35757760, 2022). "Closely related members of the Tspan8 subfamily, including CD9, CD81 and Tspan8, are associated with cancer and metastasis." (PMID 36078095, 2022). "The tetraspanin CD9 is considered a metastasis suppressor in many cancers, however its role is highly debated." (PMID 35563166, 2022). "Taken together, these results suggest that CD9+ exosomes released by HPV-positive cancer cells have a greater ability to promote cancer innervation in vivo." (PMID 35338118, 2022). "Recently, these proteins, including CD9, have been increasingly demonstrated to be closely relevant to cancer-derived exosomes by different groups, thus possessing tremendous potential as cancer biomarkers." (PMID 35757760, 2022).
cancer (continued). "For example, in clinical studies, reduced expression levels of the CD9 are correlated with progression in a range of cancers." (PMID 35204378, 2022). "Here, we employed the SW480/SW620 model to investigate the anti-cancer potential of the anti-CD9 Fab antibody." (PMID 36010551, 2022). "The chemokine C-C motif ligand-21 (CCL21) and the protein CD9 are amongst the many proteins and chemokines that play a role in cancer cell migration." (PMID 35103937, 2022). "In other cancers, such as oral cancer, exosomal tetraspanins CD9, CD63, and CD81 can be potential biomarkers for early diagnosis in high-risk patients before any clinical symptoms." (PMID 34540692, 2021). "CD9 plays an important role in many diseases, including viral and bacterial infections as well as cancer." (PMID 34493282, 2021). "For the development of exosome-based early diagnosis and analysis of cancers, tetraspanins (such as CD9, CD63, CD81, and CD82) are typically utilized as the capturing molecules for the detection of cancer-associated exosomes." (PMID 33803846, 2021). "The common exosome markers, including CD63, CD81, and CD9 and the cancer marker EGFR, are detected in A549 cell-derived exosomes with a Western Blot." (PMID 34769444, 2021). "The high expression of CD9 also suggests that cancer cells will be more aggressive and rapidly form large tumors." (PMID 35127731, 2021). "The present study not only highlights the important role of bone marrow-derived hMSCs’ CD9-mediated CCL21 regulation in cancer bone metastasis but also suggests a new distinct pharmaceutical strategy for prevention or/and therapy of cancer metastasis." (PMID 33572290, 2021). "As for detection method of CD9 expression, 12 used immunohistochemistry (IHC) tests, 3 used reverse transcription-polymerase chain reaction (RT-PCR), and 2 used flow cytometry to assess CD9 expression in the cancer cells." (PMID 34493282, 2021). "The interaction of podoplanin with the tetraspanin CD9 is mediated by CD9 transmembrane domains 1 and 2, and this interaction impairs cancer metastasis by inhibiting platelet aggregation." (PMID 34184727, 2021). "Previous reports have shown that tetraspanin CD9 can either promote or suppress cancer cell migration and metastasis, depending on the type of interacting partner, cancer type, cell type, or the migratory signal." (PMID 34429501, 2021). "CD9 is a member of the tetraspanin family and is widely expressed on the surface of various cells, including cancer cells as well as normal epithelial, endothelial, and hematopoietic cells." (PMID 34493282, 2021). "The pooled HR was 0.48 (95% CI 0.30–0.79, p = 0.003), indicating a significant association between increased CD9 expression and favorable DFS in cancer patients." (PMID 34493282, 2021). "As we know, this is the first systematic review and meta-analysis that demonstrated the prognostic significance of CD9 expression in human cancers." (PMID 34493282, 2021). "The measured CD9 levels varied considerably between conditioned cell line media, cancer patients and healthy donors but confirmed observations reported previously." (PMID 33761899, 2021). "CD9 plays a role in cellular adhesion, motility, proliferation, survival, and fertilization and is reported as a key player in the development of cancer." (PMID 34493282, 2021). "The pooled results remained unchanged, indicating a significant association between CD9 expression, OS, and DFS in cancer patients (for OS, HR 0.47, 95% CI 0.31–0.73, p = 0.001; for DFS, HR 0.48, 95% CI 0.30–0.79, p = 0.003)." (PMID 34493282, 2021). "Studies have been carried out on CD9 expression in esophageal squamous cell carcinoma and in other cancers; on salivary extracellular vesicles exosomes in cancers; and systemic diseases." (PMID 34830890, 2021).
cancer (continued). "Since B16F10, A549, and U87MG cells are well used for cancer migration/metastasis investigation, in the study we explored the role of CD9 of hMSCs or hMSC-derived exosomes on the cancer cell migration of these three cell lines." (PMID 33572290, 2021). "It was revealed that the potential cancer risk predictors are age, 20S proteasome level in exosomes, MMP9 + and MMP9+/MMP2+/EMMPRIN+ subpopulations of CD9-positive exosomes." (PMID 33773551, 2021). "In future, more relevant studies will be required to evaluate the more important role of CD9 expression in human cancer." (PMID 34493282, 2021). "It has been reported that exosomal CD9 plays an important role in intercellular communications involved in cancer cell migration and metastasis." (PMID 33572290, 2021). "For these reasons, we quantified CD9-positive plasma exosomes in the peripheral blood of patients who had cancer or benign disease with different degrees of immunosuppression including healthy controls." (PMID 34680341, 2021). "KEGG analysis identified adhesion, hematopoiesis and cancer-related proteoglycans as affected pathways (e.g. metformin: CD9, CTSL, IL5, HGF; insulin: EGF, EZR, PLCG2, TFRC)." (PMID 33690729, 2021). "Pooled hazard ratio (HR) and odds ratio (OR) with 95% confidence interval (CI) were calculated to evaluate the prognostic and clinicopathological significance of CD9 expression in cancer patients." (PMID 34493282, 2021). "We focused on A2M not only because its expression level in CD9+ cells was high but also because activation of A2M signaling was reported to promote the proliferation and survival of cancer cells." (PMID 33494824, 2021). "Our group showed that the tetraspanin CD9 negatively regulated integrin α5β1-mediated adhesion of cancer cells both to its canonical ligand fibronectin and to ADAM17 as a novel ligand." (PMID 34576100, 2021). "Our results indicated that increased CD9 expression was significantly associated with favorable OS and DFS in cancer patients." (PMID 34493282, 2021). "Regarding tetraspanin CD9, several studies showed that its knockdown is correlated with the promotion of tumoral invasion and progression, in several types of cancers, such as head and neck, skin, ovary, prostate, colon and stomach, and others." (PMID 34830819, 2021). "Our results in the present study show that similar regulatory mechanisms were exerted by CD9 on the adhesion-supporting capacity of ADAM17 when this tetraspanin was expressed on the surface of cancer-derived exosomes." (PMID 34576100, 2021). "Experimental studies using cancer cells show that CD9 basically interrupts the progression and metastasis of cancer by suppression of cancer cell proliferation and survival." (PMID 34493282, 2021). "The current study is the first to systematically demonstrate the prognostic and clinicopathological significance of CD9 expression in cancer patients." (PMID 34493282, 2021). "Controversially, the expression of CD9 in cancer cells has been reported to exert pro- and anti-migratory functions in cell migration, likely due to its modulatory activity toward associated integrin complexes and other transmembrane proteins." (PMID 33572290, 2021). "CD9 is a tetraspanin, widely considered an exosome marker in various cell types including cancer cells." (PMID 32992699, 2020). "Several researches have revealed altered CD9 or CD81 expression in other types of cancer, but to date, little is known about the mechanisms which cause the changes of CD9 and CD81 expression during cancer initiation and metastasis." (PMID 32350244, 2020). "CD9 is important for microvesicle biogenesis and sorting of the cargo proteins related with cancer progression." (PMID 32091301, 2020). "Various exosome types circulate in the blood of healthy donors and patients with different cancers, and surface proteins mainly represented by CD9, CD24, CD63 and CD81 are considered as universal markers of blood exosomes." (PMID 32218180, 2020).
cancer (continued). "The tetraspanin CD9 is considered a metastasis suppressor in many cancer types, in which low levels of CD9 protein correlate with advanced disease and poor prognosis." (PMID 32224917, 2020). "In this study, we demonstrated that a monovalent Ab directed against tetraspanin CD9 interferes with the uptake of EVs by cancer cells and primary MSCs as well as with the nuclear transfer of their cargo proteins." (PMID 30982221, 2019). "Studies have shown that CD9 plays a diverse role in both cancer and stem cell biology by regulating numerous cellular processes, such as cell adhesion, proliferation, apoptosis, motility, mitosis, and even extracellular vesicle (EV) secretion." (PMID 31191817, 2019). "It has been previously shown that CD9 can either promote or suppress cancer cell migration and metastasis, depending on the type of cancer, the type of cells involved, and the migratory signal." (PMID 31341160, 2019). "Similar to previous reports of canine exosomes found in urine and serum/plasma, the vesicles were irregularly rounded, occasionally “cup-shaped,” and immunopositive for the transmembrane tetraspanin protein CD9, known to regulate the progression of cancer." (PMID 30126376, 2018). "In the field of cancer, CD9 was both identified as a favorable prognostic marker or as a predictor of metastatic potential depending on cancer types." (PMID 30356731, 2018). "The role of CD9 in various diseases, such as viral and bacterial infections, cancer and chronic lung allograft dysfunction, is discussed." (PMID 30356731, 2018). "In the field of cancer, CD9 is suggested as a biomarker for metastatic clear cell renal cell carcinoma, not only to distinguish between cancer subtypes but also to predict the metastatic potential of renal cell carcinoma." (PMID 30356731, 2018). "In contrast, a small but detectable fraction (range 2.7 – 3.2%; mean = 2.9%) of CD9+ exosomes from non-cancer healthy controls had GFAP on their surface (a 7.9-fold difference)." (PMID 29383115, 2017). "The pro- or anti- cancer properties of CD9 is still controversial, while CD151 and TSPAN8 are assumed to display oncogenic activities." (PMID 28423546, 2017). "Serum from non-cancer healthy control individuals had very few detectable CD9+/GFAP+/SVN+ exosomes, although CD9+/GFAP+ exosomes were detectable in small numbers." (PMID 29383115, 2017). "The transcriptome of stromal cells exposed to cancer cell-derived CD9+ EVs revealed that the regulation of eleven genes, notably those involved in inflammation, relies on the nuclear translocation of EV-derived biomaterials." (PMID 28129640, 2017). "Much more has been evaluated in this field among various epithelial cancers where CD9 decline was connected with high grade cancers and worse clinical outcome." (PMID 27795705, 2016). "Some tetraspanins such as CD82, and often also CD9, are downregulated in advanced stages of cancer; their absence is a sign of poor prognosis in patients with several types of cancer." (PMID 27243007, 2016). "Recent findings suggest that the downregulation of CD9 expression is concomitant with the production of a truncated CD9 isoform through cancer specific gene fusion." (PMID 26036626, 2015). "Of these substrates, CKAP4, CD9, and CD151 have been associated with initiation and progression of cancer." (PMID 24995331, 2014). "Future studies are required to appreciate the manner in which CD9 contributes to the cancer phenotype." (PMID 24520284, 2014). "Possibly, CD9 hinders metastasis formation by prohibiting integrin-mediated motility of cancer cell lines from lung, breast, skin, gastric, pancreatic and bladder tumors in vitro." (PMID 24520284, 2014). "Paradoxically, it is increasingly appreciated that CD9 also provides cells with powerful motility in several carcinomas." (PMID 24520284, 2014). "It has been reported that CD9 negatively influences cancer cell motility by regulating the re-organization of the actin cytoskeleton." (PMID 24006899, 2013).
cancer (continued). "PCa related exosomes from clinical samples in general show the presence of some cancer related proteins such as CD9, CD81, and TSG101, Annexin A2, Fatty Acid Synthase (FASN) and a PCa specific biomarker, FOLH1 (Prostate Specific Membrane Antigen or PSMA)." (PMID 24351670, 2013). "To begin to investigate the generality of the role of the CD9/CD81 complex in regulating α3β1 function, we also created CD9/CD81-silenced A431 carcinoma cells." (PMID 23613949, 2013). "CD9 is believed to play a role in various stages of cancer development." (PMID 40530955, 2025). "In addition, p-blinatumomab specifically targets CD9- and CD3ε-expressing cancer cells, similar to BLINCYTO." (PMID 41168302, 2025). "In addition, CD9 expression exhibited differences in different cancer stages and was significantly correlated with lymph node metastasis risk." (PMID 40860827, 2025). "CD9, as a crucial membrane regulatory protein, exhibits dual regulatory roles in various cancers, yet its precise mechanism in ESCC radioresistance remains unclear." (PMID 40860827, 2025). "Furthermore, the ratio of CD9-positive to CD9-negative EV samples differed between cancer patients and healthy donors." (PMID 40565320, 2025). "CD9 is also shown to associate directly with ADAM17 on the surface of different cell types (cis interactions), including leukocytes and cancer cells, and through this association exerts an inhibitory effect on ADAM17 sheddase activity against its substrates, including TNFα, ICAM-1 or ALCAM." (PMID 38542421, 2024). "Furthermore, the presence of SRSF4-RFP, SYNCRIP-GFP, and SNU13-GFP in extracellular vesicles was confirmed through flow cytometry analysis of CD9 positive extracellular vesicles from dying cancer cells." (PMID 38898005, 2024). "The conflicting function in cancer progression may be attributed to the mechanism that involves its rather promiscuous binding and activation of certain CD9 partner molecules, allowing for different signaling pathways through those signaling transducers." (PMID 38389703, 2024). "Interestingly, some of the literature suggests that high levels of CD9, which we found to be enriched in cancer EVs, have been correlated with increased metastasis in various cancers." (PMID 38786083, 2024). "We documented the effective uptake of CD9-RFP NACS/CS bearing EVs by 5637 cancer cells as proven by the detection of red spots by confocal microscopy, indicating that the uptake kinetic is extremely rapid and the captured signal is stable as it resides inside the cells overtime." (PMID 36579638, 2023). "CD9, caveolin 1 (CAV1), tumor rejection antigen 1 (gp96), exosomal miRNAs (e.g., miR-486-5p, miR-486-3p, and miR-10b-5p are only secreted by cancer cells) have diagnostic value in HNSCC, and increased expression of HSP90, miR-31, miR-21, and MALAT1 are biomarkers for OSCC." (PMID 37046817, 2023). "Exosomes carry specific proteins (CD9, CD81, CD63, ALIX, TSG101, and HSP70), nucleic acids (DNA, miRNA, lncRNA, and circRNA), lipids, and metabolites with cancer information, making them potential cancer diagnostic biomarkers." (PMID 37016296, 2023). "However, an upregulation of cancer stemness markers such as SOX9, CD44, and CD9 implies that GBM is potentially moving towards cancer-specific stemness in the presence of NSCs." (PMID 36834653, 2023). "OSCC cells show increased secretion of exosomal heat shock protein 90 (HSP90), CD9, and epithelial cellular adhesion molecule (EpCAM) that leads to lymph node metastasis and HSP90α and HSP90β double knockdown clearly reduces the number of cancer cells." (PMID 37046817, 2023). "These might be attributed to special cancer subtypes and different antibodies used for CD9 staining." (PMID 37007105, 2023). "CD-9 expression was observed in cancerous cells at a rate of 33.3%, in CAFs at 38.1% (32 cases) and combined at 33.3% (28 cases) in patients with scirrhous cancer." (PMID 37834127, 2023).